MUC21 (mucin 21, cell surface associated)
Diseases named in the same sentence as MUC21 in open-access papers (continued):
Sharing a sentence is not in itself a finding about the gene and the disease.
cancer (15 papers, 2016 to 2026). A tumor composed of atypical neoplastic, often pleomorphic cells that invade other tissues. "MUC21, the first mucin discovered to be linked to cancer cell advancement, inhibits cell adhesion by creating steric hindrance on the cell surface." (PMID 38933439, 2024). "Further research and validation of MUC21 as a diagnostic marker could greatly impact the field of oncology by improving the accuracy and efficiency of cancer diagnosis." (PMID 38933439, 2024). "Mucin 21(Muc21)/epiglycanin is expressed on apical surfaces of squamous epithelia and has potentially protective roles, which are thought to be associated with its unique glycoforms, whereas its aberrant glycosylation is implicated in the malignant behaviors of some carcinomas." (PMID 35743163, 2022). "IHC revealed greater MUC21 expression in certain cancer cell patterns, particularly micropapillary, papillary, and lepidic, compared to cohesive tumor components in LUAD patients." (PMID 40718829, 2025). "This review aims to deliver a comprehensive overview of the glycosylation, function, and research progress of MUC21 in multiple types of cancer and infectious diseases." (PMID 38933439, 2024). "Mechanistically, MUC21 facilitates immune evasion by creating steric hindrance, preventing interactions between cancer and immune cells." (PMID 37858248, 2023). "Instead, depleting the cancer cells that express MUC21 using the ADC approach, as we have here proposed, would likely be more effective strategy for both targeted treatments and immunotherapies." (PMID 37858248, 2023). "Our genetic screens revealed that MUC21 expression on cancer cell surfaces inhibits both the cytotoxic activity of NK cells and antibody-dependent cellular cytotoxicity, but not affecting complement-dependent cytotoxicity." (PMID 37858248, 2023). "To further explore the clinical implications of MUC21 for cancer cell immunity, we analyzed its expression in various tumor types in TCGA cancer patients and corresponding normal tissues from GTEx." (PMID 37858248, 2023). "Bioinformatics tools were employed to assess the clinical implications of mucin-21 (MUC21) in cancer cell immunity." (PMID 37858248, 2023). "Because mucin family proteins share a similar structure in their N-terminus tandem repeat regions, including MUC21, it is also highly likely that MUC21 is shed from cancer cell surfaces." (PMID 37858248, 2023). "They reported that after adjusting for sex, age, smoking status, and cancer stage, there was a statistically significant reduction in overall survival for the CC genotype of rs886403 in MUC21 (HR 2.63, 95% CI 1.69–4.10, and p-value < 0.0001)." (PMID 36900282, 2023). "We found that MUC21 plays a key role in immune system evasion by creating steric hindrance that prevents the binding of cancer cells by immune cells." (PMID 37858248, 2023). "Taken together, these findings suggested that the presence of MUC21 on the surface of cancer cells can impede the cytotoxic function of NK and T cells by blocking their interaction with the cancer cells." (PMID 37858248, 2023). "Some researchers believe that MUC21 has the potential to become a new target in cancer treatment." (PMID 38933439, 2024). "Secondly, it is found that ADCs method can be used to clear the cancer cells expressing MUC21, which may be a promising targeted therapy." (PMID 38933439, 2024). "The shortening or absence of O-glycans in MUC21 is often associated with the aggressiveness of cancer." (PMID 38933439, 2024). "As we have demonstrated here, treatment with anti-PD-L1 blocking antibodies could not restore the reduced cytotoxic activity of 1G4 TCR CD8+T cells against cancer cells expressing MUC21." (PMID 37858248, 2023). "This suggests that depleting MUC21-expressing cancer cells could be a plausible strategy for improving the efficacy of immunotherapy and overcoming resistance to targeted therapies, particularly in patients with NSCLC." (PMID 37858248, 2023).
cancer (continued). "We identified MUC21, which protects cancer cells from NK and CD8+T cell mediated killing." (PMID 37858248, 2023). "We further assessed the cytotoxic activity of CAR-NK-92 cells against MUC21-expressing cancer cells to evaluate whether surface MUC21 exerts a similar inhibitory effect on CAR-NK cell responses." (PMID 37858248, 2023). "We thus investigated whether MUC21 overexpression triggers diverse transcriptional changes in cancer cells, thus enabling their immune evasion." (PMID 37858248, 2023). "Whether MUC21 expressed by carcinoma cells is involved in malignant behavior and resistance to therapy remains to be elucidated in the clinical context." (PMID 35410995, 2022). "This indicates that blocking MUC21 could be a valuable approach to improve cancer immunotherapy." (PMID 38933439, 2024). "Although the overexpression of MUC21 can improve the mucosal barrier and protective function, thus preventing infection, it often occurs abnormal expression in the development of several malignant tumors, and plays an important role in the development and metastasis of tumors." (PMID 38933439, 2024). "In addition to the ADC approach, another potential strategy is to exploit the cancer-specific glycoform of MUC21 for engineered immune cell therapies, such as CAR-T cell therapy targeting the cancer associated Tn (GalNAca1-O-Ser/Thr)-glycoform of MUC1 to control various adenocarcinomas." (PMID 37858248, 2023). "Therefore, we investigated whether the presence of membrane-bound MUC21 on cancer cells affects their interaction with immune cells." (PMID 37858248, 2023). "This suggests that inhibiting MUC21 could be a promising strategy to improve cancer immunotherapy." (PMID 37858248, 2023). "Adjacent non-malignant tissues exhibited absent or markedly weaker expression for Galectin-4, Galectin-7, MUC21, ST6GALNAC1, and ST6GALNAC2 compared to the corresponding cancer tissues." (PMID 40718829, 2025). "In summary, MUC21 can serve as an effective immunosuppressant, inhibiting CAR-T cell and CAR-NK cell anti-tumor functions, thereby protecting the cancer cells from attack by NK and CD8+T cells." (PMID 38933439, 2024). "Most of the genes showed an increase in gene expression during the stages of cancer, particularly in the last two stages, except for NDRG2, FAM3D, KRT78, SLURP1, MUC21, and CRCT1, which showed a significant drop in gene expression compared to normal tissue." (PMID 37917867, 2023). "This unique mechanism supports the non-redundant role of MUC21 in cancer immune surveillance as it is distinct from MUC1, which shows a highly correlated expression with MUC21 in NSCLC and has an intracellular activity in cancer cells." (PMID 37858248, 2023). "Effect of MUC21 expression increase on survival was significant in both univariate (q = 0.005) and multiple regression (q = 0.003) showing a hazard ratio (HR) of 1.9 and 2.1 respectively, although only for KIRP, which may signify an underlying harmful role of MUC21 functioning in cancer." (PMID 28978023, 2017). "A recent study of mucin expression in a human epithelial carcinoma cell line (A549) showed a strong induction of MUC8, MUC15, MUC20, MUC21, and MUC22 mediated by RSV infection." (PMID 29162850, 2017). "Our present study findings have revealed that MUC21 expression by cancer cells attenuates NK cell mediated ADCC by inhibiting the conjugation between cancer and NK cells without affecting antibody binding." (PMID 37858248, 2023). "MUC21-mediated immune evasion is thought to solely rely on steric hindrance through its highly glycosylated TR domain rather than via a direct modulation of the intrinsic signaling of cancer cells, since there are no reported intracellular activities of MUC21." (PMID 37858248, 2023). "Targeting MUC21 could present an opportunity to enhance the effectiveness of immunotherapy and overcome resistance in NSCLC by circumventing the immune evasion mechanisms employed by cancer cells." (PMID 37858248, 2023).
cancer (continued). "Although the specific glycoforms of MUC21 that are relevant in normal and malignant tissue are not yet well understood, a prior study has reported that an O-glycan recognizing MUC21 antibody only binds to the luminal side of esophageal squamous epithelial cells, but not to carcinoma cells." (PMID 37858248, 2023). "We also found that six genes (TBP, EP400, DSPP, MUC21, MLLT3, and MUC2) were under negative selection in more than five cancer types." (PMID 28938601, 2017).
tumor (9 papers, 2020 to 2026). "MUC21 has been found to have a significant impact on tumor development and is also involved in various essential biological processes." (PMID 38933439, 2024). "Given the limited understanding of how mucin molecules expressed in tumor cells modulate NK cell cytotoxicity, we focused on MUC21 for further analysis." (PMID 37858248, 2023). "In addition, the highly glycosylated tandem repeat domain of MUC21 on the cell surface impairs cell–cell and cell–matrix adhesion via steric hindrance, potentially contributing to tumor metastasis through enhanced cell migration and invasion." (PMID 40718829, 2025). "This suggests that MUC21 may play a crucial role in the progression of tumors, offering valuable insights into its specific functions in the field of tumor biology." (PMID 38933439, 2024). "For example, the presence of MUC21 glycoform shows a significant correlation with tumor growth." (PMID 38933439, 2024). "Further investigation into the recognition and unique functions of MUC21 glycoform may provide novel strategies for tumor diagnosis and treatment." (PMID 38933439, 2024). "Moreover, it is a good method to treat tumor by regulating the downstream signal molecules of MUC21." (PMID 38933439, 2024). "Furthermore, the MUC21 on the surface of tumor cells inhibits the interaction between cytotoxic T cells and MHC molecules on tumor cells." (PMID 38933439, 2024). "We investigated whether surface MUC21 expression could render tumor cells resistant to antibody-dependent NK cytotoxicity using NK-92 cells stably expressing human CD16 (NK-92-CD16)." (PMID 37858248, 2023). "Although the precise role of MUC21 in tumor-immune interactions remains poorly understood, a recent study has reported that this mucin negatively affects macrophage-mediated antibody-dependent cellular phagocytosis (ADCP) through its anti-adhesion properties against macrophages and antibodies." (PMID 37858248, 2023). "However, the presence of MUC21 prevents T cells from recognizing antigens, thereby limiting the anti-tumor efficacy of ICIs." (PMID 37858248, 2023). "Therapeutic strategies targeting MUC21 may offer a promising approach, particularly in LUAD subtypes characterized by micropapillary architecture and EGFR mutations, where its expression is implicated in tumor progression." (PMID 40718829, 2025). "They indicated that MUC21 may inhibit cell-cell extracellular matrix interactions and interfere with cell-cell adhesion, thus suppressing cell-cell adhesion molecules and surface integrins, and ultimately impacting tumor metastasis." (PMID 38933439, 2024). "Their research also indicated that in vitro, MUC21 has the ability to enhance the activity and movement of GBM cells, as well as stimulate tumor growth in vivo." (PMID 38933439, 2024). "We prepared two new mAbs, 1A4-1 and 18A11, that specifically recognize Muc21 with distinct glycoforms, and used them to profile the glycan structures of Muc21 on TA3-Ha cells in vitro in culture and in situ in tumor tissue." (PMID 35743163, 2022).
infection (5 papers, 2015 to 2025). The state of being infected such as from the introduction of a foreign agent such as serum, vaccine, antigenic substance or organism. "Studies have shown that the novel transmembrane mucin MUC21 is involved in the defense against infection by pathogenic microorganisms." (PMID 38933439, 2024). "This indicates that changes in the MUC21 gene are closely related to pathogen infection, and its expression has certain protective effects on the epithelial cells." (PMID 38933439, 2024). "In gECs, E. gingivalis infection increased mucin (MUC1: 3.6×, MUC21: 14.4×) and interleukin secretion (IL-8, IL-1B: >6×, P = 0.019)." (PMID 40116481, 2025). "In contrast, G5P infection decreased expression of transmembrane mucin genes significantly (MUC12, MUC16 and MUC21) or numerically (MUC1, MUC4, MUC13 and MUC20)." (PMID 37848925, 2023). "Overexpression of TM mucins MUC1, MUC4 or MUC21 reduced infection by SARS-CoV-2 compared to cells with a non-targeting guide (NTG)." (PMID 37561789, 2023). "Our data indicate that the MUC expression by RSV and hMPV differs significantly, as we observed a stronger induction of MUC8, MUC15, MUC20, MUC21, and MUC22 by RSV infection while the expression of MUC1, MUC2, and MUC5B was dominated by the infection with hMPV." (PMID 25977598, 2015).
adenocarcinoma (2 papers, 2019 to 2023). A common cancer characterized by the presence of malignant glandular cells. "Most adenocarcinomas expressed MUC21 (if tumors with very focal expression were included, a positive frequency, for example MUC21 expression detected by the polyclonal antibody, was 77.6% (187/241) of whole LADCs, and 87.1% (101/116) of EGFR-mutated LADCs)." (PMID 30973916, 2019).
MUC21 also shares sentences with these, for which no sentence is quoted: epithelioid mesothelioma (3 papers); lung squamous cell carcinoma (2); type 1 diabetes (2); brain cancer (1); cervical squamous cell carcinoma (1); colon adenocarcinoma (1); cystic fibrosis (1); endocrine disorder (1); esophageal carcinoma (1); infectious disease (1); intestinal diseases (1); laryngeal squamous cell carcinoma (1); leukemia (1); liver cancer (1); lymphoma (1); microcephaly (1); myeloma (1); non-small cell lung carcinoma (1); Obesity (1); oral squamous cell carcinoma (1); ovarian carcinoma (1); ovarian clear cell cancer (1); pancreatic adenocarcinoma (1); rectal adenocarcinoma (1); respiratory diseases (1); schizophrenia (1); tongue squamous cell carcinoma (1); Type 1 diabetes mellitus (1); uveal melanoma (1).